CRP (C-reactive protein)
Diseases named in the same sentence as CRP in open-access papers (continued):
Sharing a sentence is not in itself a finding about the gene and the disease.
depression (continued). "Of interest in this context is however the fact that high harm avoidance and low self-directedness, i.e. the two traits displaying significant associations with CRP in this study, are important predictors of depression." (PMID 18384670, 2008). "Moreover, a meta-analysis of 20,791 children and adolescents associated concurrent depression with CRP and IL-6, while depression proved a significant predictor of IL-6." (PMID 41515266, 2026). "In conclusion, our results indicate that a diet with a high pro-inflammatorypotential is associated with a higher risk of depression and anxiety inadolescents, and inflammation markers as assessed by CRP levels are one of themain mediators that may occur." (PMID 40110388, 2025). "Longitudinal studies have confirmed bidirectional associations between CRP, IL-6 and depression." (PMID 40912718, 2025). "The small sample size may restrict the detection of changes in serum CRP levels and hinder the identification of potential associations among depression, cognition, and sleep." (PMID 40673224, 2025). "Depression in cancer patients can be classified as an immuno‐inflammatory disorder, associated with elevated levels of proinflammatory mediators such as cytokines and acute phase proteins like CRP and haptoglobin." (PMID 40387308, 2025). "Moreover, CRP, neutrophil, platelet, leukocytes, and neutrophil-to-lymphocyte ratio significantly mediated the association between pain and depression, suggesting underlying mechanisms driven by systemic inflammation." (PMID 40173244, 2025). "The vegetable-based dietary pattern, rich in antioxidants, fiber, and polyphenols, has been associated with lower levels of systemic inflammation, as indicated by biomarkers such as C-reactive protein and interleukin 6, both of which are implicated in depression and age-related physical decline." (PMID 41450553, 2025). "For example, using three measures of CRP from ages 9 to 18 years, Osimo et al36 showed that individuals who were characterised as having increasing CRP levels over time had a higher risk of moderate or severe depression at age 18 years." (PMID 40814293, 2025). "However, it is known that in the general population and in PLWH, markers of inflammation or immune activation (such as TNFα, CRP, IL-6) are closely associated to both depression and sleep quality." (PMID 40313235, 2025). "This suggests that evaluating IL-6 vis-à-vis fibrinogen and CRP may better capture nuanced pathways through which inflammation interacts with psychosocial factors to influence depression symptom risk." (PMID 41210298, 2025). "For example, patients with higher body mass index and CRP may respond worse to SSRIs, which are typically the first line treatment for depression, underlying the importance of treatment personalization in this group." (PMID 40345207, 2025). "We hypothesize that there will be an association between C. trachomatis and depression, and CRP will modify this effect." (PMID 41153310, 2025). "Although previous studies have examined the relationship between some inflammatory biomarkers (such as cytokines, C-reactive protein) and depression, these biomarkers are relatively transient and susceptible to short-term influences, and there are conflicts between different research conclusions." (PMID 40276074, 2025). "Potential mechanisms involve sleep-related inflammation: poor sleep quality correlates with elevated pro-inflammatory cytokines (e.g., IL-6 and CRP), which may disrupt neural circuits regulating mood, thereby increasing depression risk." (PMID 40218955, 2025). "Indeed, the association of CRP and depression was substantially attenuated in this study, as well as many others, following adjustment for potential confounders." (PMID 40348744, 2025). "Moreover, elevated CRP was once again linked to comorbid depression and high pain levels, reinforcing its role as a mediator between emotional and somatic symptomatology." (PMID 41373439, 2025).
depression (continued). "Interestingly, they have also found that poor sleep quality is also associated with increased C-reactive protein levels in this category of participants, which reinforces the role played by inflammation in depression." (PMID 40313235, 2025). "More direct evidence of the relationship between inflammation and depression has been demonstrated by an increase in interleukin-6 (IL-6), C-reactive protein (CRP), and tumor necrosis factor-alpha (TNF-α) associated with a higher risk of depression and increased symptoms." (PMID 41333345, 2025). "Inflammatory biomarkers, including CRP and calprotectin, were also significantly reduced, indicating lower systemic inflammation—a factor potentially contributing to improved mood and reduced risk of depression." (PMID 41142011, 2025). "Our findings indicate that the higher pro-inflammatory potential of diet is associated with a higher risk of depression and anxiety, and this association may be mediated by CRP for depression and anxiety, WC, and BMI-z score for only depression." (PMID 40110388, 2025). "In addition, depression was associated with increased tender joint counts, and anxiety was associated with elevated CRP levels." (PMID 39504461, 2025). "Consequently, we performed analyses to observe the potential associations between depression and elevated inflammatory markers such as CRP, ESR and the anti-CCP, RF-IgM, and RF-IgA antibodies." (PMID 40837576, 2025). "Elevated levels of inflammatory markers such as C-reactive protein and interleukin-6 have been associated with depression, and these markers may underlie the link between the PINI and mortality outcomes." (PMID 40718002, 2025). "Concerning the covariates analyzed, we found that being a woman, having oral cavity cancer (rather than larynx), worse performance in daily activities, history of depression or anxiety, daily smoking, higher CRP, and flatter cortisol slope were associated with more PNS." (PMID 40877705, 2025). "Our observation that CRP ≥3 mg/L amplified CVD risk exclusively in depressed patients (OR=1.524 vs. 1.324 in low-inflammation counterparts) suggests that depression may prime the vascular endothelium to inflammatory insults." (PMID 40904459, 2025). "Moreover, some inflammatory markers, including C-reactive protein, partially mediated the association between composite pain scores and depression risk." (PMID 40173244, 2025). "Moreover, sleep fragmentation and decreased deep sleep have been linked to increased systemic inflammation, as reflected in elevated markers such as interleukin-6 (IL-6) and C-reactive protein, which have also been implicated in the etiology of depression." (PMID 41294789, 2025). "Certain personality traits, such as high levels of anger, hostility, anxiety, and depression, have been associated with elevated C-reactive protein(CRP) levels and sympathetic nervous activation, both of which contribute to an increased risk of atherosclerosis." (PMID 40093753, 2025). "On the other hand, depression is associated with elevated peripheral inflammatory markers such as C-reactive protein (CRP), which may exacerbate local renal inflammation and contribute to kidney damage." (PMID 40595897, 2025). "However, increased IL-6 and C-reactive protein (CRP) levels have been consistently associated with suicidal behaviour in people with depression and anxiety, independently of depression severity." (PMID 40420573, 2025). "The fact that, in contrast to the previous observation for CRP, our immunometabolic and immune cell-mediated factors are associated with mental health in non-users highlights the multi-faceted nature of the immune response in depression." (PMID 39911945, 2025). "While bidirectional associations between insomnia and these outcomes exist, the patterns of anxiety–depression–CRP associations within different insomnia severity groups remain unclear." (PMID 41048872, 2025).
depression (continued). "Oxidative damage further promotes the release of mtDNA, which triggers neuroinflammatory responses, and mtDNA variants associated with depression and anxiety may underlie elevated CRP levels and psychiatric symptomatology." (PMID 41226736, 2025). "Additionally, physical training has been shown to regulate the inflammatory response by reducing levels of inflammatory markers like C-reactive protein and cytokines, which has been associated with a reduction in depression." (PMID 38836958, 2024). "Furthermore, variations in the association between depression and hs-CRP levels have been observed in studies conducted in diverse populations, including differences related to gender, age, race, or other potential confounders." (PMID 38596631, 2024). "Some evidence suggests that the association between CRP and depression could be confounded by other cytokines, such as IL-6." (PMID 38699297, 2024). "Numerous studies over the past 20 years have indicated that chronic low-grade inflammation may be associated with depression, with elevated CRP levels often observed in patients with depression." (PMID 39329797, 2024). "C-reactive protein is implicated in cognitive impairment, Alzheimer’s disease, and depression." (PMID 39685972, 2024). "Second, we conducted genetic risk score (GRS) and MR analysis to test whether genetic variants regulating levels and activity of CRP, IL-6, and GlycA were causally related with depression/cognitive performance." (PMID 38699368, 2024). "This may include matched-design studies to investigate whether elevated peripheral hs-CRP levels contribute to the risk of depression onset or recurrence." (PMID 38596631, 2024). "In addition, low levels of physical activity, often associated with depression and hemodialysis, can contribute to inflammation and elevated CRP levels." (PMID 38255209, 2024). "Additionally, research has reported gender-specific associations between CRP levels and symptoms of depression and anxiety, with significant positive correlations observed only in females." (PMID 39554848, 2024). "However, the magnitude of the association between CRP and depression is still unclear due to the significant variability in the methods of controlling potential confounders and quality measures." (PMID 38468463, 2024). "We hypothesized that both circulating CRP levels and genetically predicted inflammatory biomarkers (i.e., CRP, IL-6, sIL-6R, and GlycA) would be associated with depression, cognitive task performance, affect, and anxiety." (PMID 38699368, 2024). "A multivariable regression analysis demonstrated that older age (p = 0.001), the presence of inflammation (high concentration of CRP) (p = 0.045), the presence of anxiety (p = 0.008), and depression (according PHQ-9 scale, p = 0.004) were associated with frailty syndrome among the HF patients." (PMID 39685803, 2024). "Genetic risk scores (GRS) were calculated to determine whether GRS for inflammatory markers (CRP, IL-6, IL-6R, sIL-6R, GlycA) were associated with depression/anxiety, affect and cognitive outcomes." (PMID 39149475, 2024). "Elevated CRP levels may serve as an indicator for medical professionals, signaling a potential risk of depression in these patients." (PMID 38255209, 2024). "Our study also showed that the abundance of Blautia was positively correlated with serum CRP level, therefore, Blautia may cause depression and anorexia by promoting inflammation." (PMID 38698338, 2024). "Of note, neuroinflammation has furthermore been implicated in the pathophysiology of depression, whereas increased inflammatory markers, such as C-reactive protein (CRP) or interleukin-2 (IL-2), have been specifically described to be more associated with the atypical subtype of depression." (PMID 38172332, 2024). "Moreover, these regional brain volumes and three inflammatory markers—C-reactive protein, neutrophils, and leukocytes—significantly mediate associations between frailty and depression." (PMID 38782943, 2024).
depression (continued). "In a longitudinal sample of older adults from the Health and Retirement Study, higher diet quality, as measured by the HEI-2015, was associated with better lipid and C-reactive protein (CRP) profiles and decreased likelihood of depression and functional deficits." (PMID 38532045, 2024). "Building on this work, tools can be developed to identify individuals at risk for developing immunometabolic depression (e.g., using blood tests of high-density lipoprotein and C-reactive protein levels) and target them for cholesterol-lowering or anti-inflammatory medical interventions." (PMID 37693619, 2024). "A meta-analysis showed that high levels of CRP and IL-6 are associated with future depressive symptoms, suggesting that inflammatory cytokines are potentially important biological markers in depression research." (PMID 38377025, 2024). "Gender differences in the inflammatory response linked to depression and the influence of sex hormones may contribute to the stronger association of depression with serum hs-CRP levels in men compared to women." (PMID 38596631, 2024). "The absence of a link between chronotype and systemic inflammation as measured by CRP levels indicates that other mechanisms may underlie the relationship between sleep patterns and depression symptoms." (PMID 39562745, 2024). "Further evidence supporting the hypothesis that inflammation is a cause rather than a consequence of depression is provided by a Mendelian randomization analysis of a UK Biobank sample, demonstrating that IL-6 and CRP are causally linked with depression." (PMID 37848651, 2024). "Numerous prior investigations have proposed that heightened peripheral CRP levels may augment the risk of depression and serve as predictors for depressive symptoms." (PMID 38596631, 2024). "Increased levels of CRP were linked to a higher incidence of depression." (PMID 38596631, 2024). "Our study suggested that GCKR may affect NAFLD through modifiable risk factors, such as waist circumference, smoking, depression, C-reactive protein levels, galectin-3, and HDL cholesterol." (PMID 38782984, 2024). "Furthermore, compared to those with high 10-year cardiovascular risk, MDD patients with low 10-year cardiovascular risk presented lower age/CRP levels/body mass index and higher Insomnia Severity Index/Beck Depression Inventory scores." (PMID 38792664, 2024). "In addition, mendelian randomization analyses suggested that IL-6, CRP are likely to be causally linked with depression." (PMID 37344456, 2023). "However, the associations between CRP and depression and physical activity were similar for patients and controls." (PMID 37444517, 2023). "Each standard deviation increase in preoperative logarithmically transformed high sensitivity CRP levels was associated with an increased odds of developing pre-operative depression (OR: 1.16, p = 0.001) and postoperative depression at 6 months (OR: 1.15, p = 0.002)." (PMID 37928924, 2023). "These authors tested the hypothesis that low-grade inflammation might be a potential mechanism, using prospective data from the UK Biobank to examine vascular risk factors (VRFs) and C-reactive protein associations to depression outcomes." (PMID 37881584, 2023). "Moreover, we found a positive association between peripheral CRP and overall severity of depression, which was consistent with meta-analytic evidence." (PMID 36831896, 2023). "For example, sex could moderate within-person CRP-depression associations and relate to the hypothalamic–pituitary–gonadal axis, corticotropic-releasing hormone, cell death programming, and mitochondrial differences." (PMID 35924730, 2023). "Finally, the vast majority of research that has examined the associations between insomnia, inflammation, and depression, has assessed CRP and circulating levels of IL-6 and TNF." (PMID 36879913, 2023).
depression (continued). "In the autoregressive model, baseline CRP was positively associated with CRP in 2015 (ßstd = 0.26, p < 0.01), baseline depression prospectively predict depression in 2013 (ßstd = 0.47, p < 0.01), and depression in 2013 prospectively predicted depression in 2015 (ßstd = 0.49, p < 0.01)." (PMID 36860788, 2023). "Similarly, UBE2Z, GIP and IGF2BP1 have been linked to CAD, T2D, and depression-related traits such as insomnia, BMI, educational attainment, CRP levels, platelet count and smoking." (PMID 37390107, 2023). "IL-6, CRP, and triglycerides (TG) may be causally related to depression and therefore may be targets for treatment and prevention of mental sickness." (PMID 38084332, 2023). "Age and BMI were positively associated with CRP and depression in 2011, BMI was positively associated with depression in 2013, age and BMI were positively associated with CRP in 2015, and BMI was negatively associated with depression in 2015." (PMID 36860788, 2023). "Although CRP itself cannot cross the blood–brain barrier, elevated CRP levels probably indicate elevated levels of cytokines, which can cross this barrier and have been proven to be associated with depression." (PMID 37049401, 2023). "Several significant mtDNA × CRP associations were found for anxiety and depression, respectively." (PMID 37344456, 2023). "After adjusting for potential confounders, applying two different statistical models, and conducting a stratification analysis, we consistently found serum magnesium levels to be inversely associated with depression scores, especially among people with elevated CRP levels." (PMID 37049401, 2023). "Similarly, a 2014 MR study of the general Danish population revealed that, in contrast to genetically elevated CRP levels, elevated plasma CRP levels are associated with an increased risk of depression and psychological distress." (PMID 37996851, 2023). "Similarly, depression is associated with elevated C-Reactive Protein (CRP) and Interleukin-6 (IL-6) levels, while anxiety is associated with an increase in CRP, TNF-α, and Interferon-γ (IFN-γ) levels." (PMID 37251220, 2023). "Furthermore, a meta-analysis of 22 studies concluded that depression in children and adolescents is associated with increased inflammatory factors such as IL-6 and CRP." (PMID 37840796, 2023). "For example, levels of peripheral C-reactive protein (CRP)—an acute phase reactant that is synthesized by hepatocytes in response to pro-inflammatory cytokines (in particular interleukin-6 (IL-6))—are associated with overall depression severity." (PMID 36831896, 2023). "Higher CRP levels suggest a higher risk of developing a new type of depression." (PMID 36769799, 2023). "For example, a meta-analysis reported longitudinal associations between parental absence during early development and elevated CRP in adults suggesting a mechanism that may mediate the susceptibility to depression." (PMID 36831896, 2023). "In addition, 5 common mtDNA shared with anxiety and depression were found in MiWAS, and 4 common mtDNA variants were detected to interact with CRP for anxiety and depression, such as m.9899T>C(MT-CO3)." (PMID 37344456, 2023). "Notably, previous evidence suggests that increased appetite is a key factor that drives associations of depression with BMI and CRP." (PMID 36462595, 2023). "Indeed, IL-6 and CRP levels are associated with depression severity, predict cognitive impairments in depression, and are further aggravated by acute stress." (PMID 37764744, 2023). "Measuring the levels of CRP may identify patients at risk of developing depression following cardiac surgery." (PMID 37928924, 2023). "However, only CRP was associated with greater depression and less physical activity among both patients and controls." (PMID 37444517, 2023). "Epidemiology studies also demonstrated the associations between CRP and anxiety, depression." (PMID 37344456, 2023).